CD4 (CD4 molecule)
Diseases named in the same sentence as CD4 in open-access papers (continued):
Sharing a sentence is not in itself a finding about the gene and the disease.
tumor (continued). "In antitumor and antichronic viral responses, CD4+ T cells provide indirect assistance to the cytotoxic CD8+ T cells relayed by DCs, interact with B cells, macrophages and NK cells to indirectly modulate response, and inhibit tumor blood vessel formation." (PMID 37829505, 2023). "This in turn aids in the suppression of effector CD4+ and CD8+ T cell function, required for anti-tumor immune responses, and correspondingly induces suppressive regulatory T cells, which further contribute to the suppression of effective anti-tumor immune responses." (PMID 38136258, 2023). "CD4+ TILs and CD8+ TILs were quantitatively related to PD-L1-positive tumour cells." (PMID 37372432, 2023). "In the immunological environment, CD4+ T cells express a low level of EGFR, one of the ErbB family, and the expression level of EGFR is higher on Treg cells than that on effector CD4+ or CD8+ T cells in tumor or inflammatory microenvironment." (PMID 37666819, 2023). "Besides, we analyzed the levels and distributions of CD3+CD4+ T and CD3+CD8+ T cells in the tumor microenvironment using IF." (PMID 36999930, 2023). "Moreover, LAG3 also helps maintain CD8+ T cells in a tolerogenic state and has been reported to play an issue role in CD4+CD25+Foxp3+Tregs suppressive function, thus favouring the escape of the tumour from immune surveillance in various human cancers." (PMID 36980527, 2023). "This is likely facilitated in CD4+ CAR T cells that do not require major histocompatibility complex (MHC) class II expression on tumor cells for contact-dependent cytotoxic activity (as compared to conventional CD4+ T cells)." (PMID 37248395, 2023). "Consistent with this Th1 antigen–specific cytokine profile, mice vaccinated with the CD4 vaccine only had a significantly higher proportion of Tbet+CD4+ Th1 cells and significantly lower GATA3+CD4+ Th2 cell population within the tumor compared with mice vaccinated with the CD8 vaccine." (PMID 38063199, 2023). "In tumor-infiltrated Treg cells, metformin inhibits FOXP3 expression in an AMPK-dependent manner through the activation of mTORC1, which acts as a negative regulator for FOXP3 induction in naive CD4+ T cells." (PMID 37686159, 2023). "At early stages of tumor response (i.e., when tumor’s progression stopped), we indeed showed that Lipo-MP-LPS induces an early tumor infiltration by CD3+CD4+CD25+ T helper cells, but not Treg, and increases the levels of CD68+CD86+ M1 macrophages in tumors." (PMID 37760603, 2023). "Furthermore, in LCNEC tumor tissues, infiltration of CD3+, CD4+, and CD8+ lymphocytes as well as slightly CD20+ cells were observed, indicating tumor immunity and T cell involvement." (PMID 38035072, 2023). "Studies in other cancer types have reported that complement activation promotes tumour growth and suppresses anti-tumour immunity including levels of CD8+ and CD4+ TILs58–61 which is consistent with the inferior survival outcomes in the CD3+ TIL-low UPS and DDLPS patients in our cohort." (PMID 37386008, 2023). "We found that high PRS patients had higher immune infiltration scores but more tumor-promoting cells (such as M2 macrophages and neutrophils), while low PRS patients had more cytotoxic cells (such as CD8+ T cells and follicular helper CD4+ T cells)." (PMID 37477536, 2023). "The results indicated that PDIA3 was positively correlated with tumor-infiltrating CD8+ T cells (P = 5.26E-05) and macrophages (P = 2.56E-03), while it exhibited a negative correlation with tumor-infiltrating CD4+ T cells (P = 2.34E-03)." (PMID 37909009, 2023). "In several tumor models, metformin can modulate tumor-infiltrated effector immune cells, CD8+, CD4+ T cells, and natural killer (NK) cells, as well as suppressor immune cells, T regulatory cells, tumor-associated macrophages (TAMs), and myeloid-derived suppressor cells (MDSCs)." (PMID 37686159, 2023).
tumor (continued). "However, RT elicited increased CD8+ T cells, decreased CD11b+F4/80+ myeloid cells, augmented CD8+ and CD4+ cell proliferation and IFN-γ production in tumor-draining lymph nodes in situ, reshaping the immune microenvironment of liver metastasis." (PMID 37833255, 2023). "However, accumulating evidence highlights the relevance of CD8+ T cell cooperation with B cells and CD4+ T cells and the formation of tertiary lymphoid structures (TLS) in nurturing adaptive immune cell interactions in inflamed and tumor tissue." (PMID 36836910, 2023). "Additionally, we collected tumor tissues from 26 LUAD patients and performed immunohistochemical experiments to detect the proportion of positive cells for CD8 and CD4 surface antigen, and TAGAP in immune infiltrating cells." (PMID 37744350, 2023). "We quantified changes in the phenotype, distribution and intercellular contacts of subsets of tumor-associated macrophages (TAMs), CD4+ and CD8+ T cells, and regulatory T cells (Tregs) in PV and non-PV various areas of the stroma and tumor cell islands." (PMID 38090569, 2023). "CD4+, CD8+, and CD45+ tumor-infiltrating immune cells were analyzed in all tumor samples." (PMID 37761986, 2023). "Moreover, in responsive tumor samples, TIM-3-PD-1 BsAbs indirectly promoted B cell activation by inhibiting the production of PD-1+CXCL13+CD4+ T cells." (PMID 37670328, 2023). "Furthermore, it has been noted that HPV+ neoplasms contain significantly higher densities of CD3+, CD4+, CD8+, CD20+ antigens and PD-1+ cells compared to HPV− tumours, with a trend towards the increased density of Foxp3+Treg cells." (PMID 36980527, 2023). "Next, we compared the proportion of CD4, CD8, CD19, CD68 and Foxp3 positive cells in lymphocytes of patients with high and low expression of ICOSLGTCs, as well as the proportion of CD4, CD8 positive cells and Fopx3+ cells, and divided them into invasive Frontier and tumor center for analysis." (PMID 37842091, 2023). "We also found that ESCC patients with a smoking history had a shorter distance of CD4+PD-1− T cells to tumor cells before treatment than those without." (PMID 37275884, 2023). "We proposed that CD4+ effector T cells are efficiently activated in tumour tissues by antigen-presenting immune cells that constitutively express MHC-II, whereas CD8+ T cells require MHC-I-restricted antigen presentation by tumour cells." (PMID 37316667, 2023). "An increase in CD4+ T-lymphocyte content and CD4+/CD8+ ratio means that the tumor is still in an early clinical stage, while an increase in CD8+ T-lymphocyte content means that the tumor has escalated to an advanced stage." (PMID 37206348, 2023). "Using poly-ICLC and/or resiquimond as an adjuvant, a trial found that a human anti-DEC-205 monoclonal antibody fused with the tumor antigen NY-ESO-1 produced a humoral and NY-ESO-1-specific CD4 and CD8 cells response, leading to partial clinical responses without toxicity." (PMID 38140187, 2023). "The CD4+ and CD8+ T cell populations in splenocytes in FeMOF-based cancer vaccines in large size (dLLC-ML) and small size (dLLC-MS) are significantly higher than saline group and free dLLC autologous tumor antigens group." (PMID 38259474, 2023). "Due to the relevance of tumor-infiltrating T lymphocytes in the anti-cancer immune response, we further assessed TMEM123 expression in CD8+ and CD4+ T lymphocytes infiltrating CRC tissues by multiple immunofluorescence confocal microscopy on cryopreserved CRC tissues (N=4 samples)." (PMID 37426665, 2023). "Active fibrosis and infiltration of CD4/8-positive T-lymphocytes were observed around 1 cm of the tumor, with no necrosis or vessel embolization." (PMID 37878146, 2023). "Additionally, it was postulated that the rise in CD4+ (51.5%) and CD8+ (35.1%) in the spleen tissue would prevent metastasis and recurrence of the tumor." (PMID 36987269, 2023).
tumor (continued). "We investigated the bone remodeling markers RANK/RANKL/OPG, the endothelial glycoprotein CD146, and biomarkers of the immune environment (CD163 and CD68 of macrophages, CD4+ and CD8+ of tumor-infiltrating lymphocytes (TILs), and an immune checkpoint PD-1/PD-L1)." (PMID 36831348, 2023). "In performing a correlation analysis between the various types of tumor-infiltrating immune cells, we found a significant negative correlation between memory-resting CD4 T-cells and CD8 T-cells as well as between CD49a NK-cells and CD8 T-cells." (PMID 38107324, 2023). "Compared with that in M/PDA, the proportion of tumour-infiltrating CD4-Treg cells in GSRC was higher, and the difference was not statistically significant (t-test, p = 0.25)." (PMID 37225691, 2023). "Consistent with the increased tumor growth, Zeb1-dcKO mice showed a marked decrease in the recruitment and activation of effector CD8+ T cells and a mild reduction in numbers of effector CD4+ T cells in B16F10 tumors despite normal cDC1 infiltration." (PMID 37863917, 2023). "A recent study from Rosenberg and colleagues demonstrated that among 20 confirmed NeoAg-specific TCRs isolated from CD4+ TILs found in human tumors, none was able to directly recognize autologous tumor cells." (PMID 37400675, 2023). "TEM cells were the predominant population throughout the course of tumour outgrowth (>63% and >52% of total CD4+ and CD8+ TILs, respectively), but early-stage tumours (D7) exhibited substantial infiltration by naïve CD44LOCD62L+ TN cells (24% and 25% of total CD4+ and CD8+ TILs, respectively)." (PMID 37153625, 2023). "In order to understand the specific effect of SERPINE1 expression on an immune cell, we then used the TIMER database to analyze the correlation between SERPINE1 expression in STAD and tumor purity, B Cells, CD8+ T Cells, CD4+ T Cells, macrophages, neutrophils, and dendritic cell infiltration levels." (PMID 36697459, 2023). "In addition, the PANoptosis score was significantly correlated with the tumor microenvironment, the infiltration levels of most immune cells (i.e.NK cells, CD8+ T cells, CD4+ T cells, DC cells), and immune-related genes." (PMID 36890219, 2023). "Here we show that contact with activated CD4+ T-cells enables human ex vivo cDC1, but no other DC types, to induce a CTL response to cell-associated tumor antigens." (PMID 36639382, 2023). "Th1 cytokines and cytotoxic mediators are essential for T cells to maintain the GVL effect and kill tumor cells, yet they also lead to the damage of healthy host tissues, More specifically INF-γ and TNF-α secretion by donor CD4 T cells are the hall mark of persistence of GvHD mediators." (PMID 36901757, 2023). "Also, after injection of these products into mice bearing IMR5 NB cells, on day 8, these tumours contained CD8 and CD4 effector T cells in the TME." (PMID 37887559, 2023). "Notably, in ascites, the CD56 of frequency was lower in M1xx CD4+ CAR T cells (p<0.05) and CD8+ tumor-infiltrating M1xx CAR T cells (p<0.01), whereas high M28z and MBBz CAR T cells." (PMID 36746513, 2023). "Using tumor cells transduced with ICOSL as a vaccine, the authors observed improved effects of antitumor T effector cells, which is reflected by a higher ratio of intratumoral CD8/Treg and CD4+ Teff/Treg cell." (PMID 38127899, 2023). "Additionally, to confirm the role of IGSF6 in antigen processing by M1 macrophages in vivo, we injected CD4+ T cells, LUAD cells, and M1 macrophages with IGSF6 knockdown into nude mice and monitored tumor progression." (PMID 38037023, 2023). "TCF1 has both WNT-dependent and -independent functions and has not been well studied in tumor-infiltrating CD4+ T cells." (PMID 36239683, 2023). "Collectively, our study provides strong evidence that human CD4 CTLs are capable of killing tumor cells directly and controlling tumor growth independent of CD8 T cells." (PMID 37185301, 2023).
tumor (continued). "Only very few CD4+ effector T cells, representing 1% of tumour-infiltrating immune cells, locate at the tumour invasive margins where they interact with CD11c+MHC-II+ antigen-presenting immune cells and indirectly eliminate tumours." (PMID 37316667, 2023). "CD4+ T cells and TH cells played an important supportive role in the anti-tumor immune effect, and Gamma delta T cells killed tumor cells through a non-MHC-restricted manner." (PMID 36742386, 2023). "In addition to MDSCs and Treg cells, T cells, including CD4 + T cells and CD8 + T cells, have an important role in tumor rejection." (PMID 36853330, 2023). "While depletion of CD4+ T cells did not alter the tumor control, depletion of CD8+ T cells completely abrogated the antitumor activity of the combination therapy (p < 0.001 on day 22)." (PMID 36949064, 2023). "These immunosuppressive cells hinder CD4 and CD8 T cell response as well as the ability of natural killer (NK) and antigen-presenting cells (APC) to exert effective tumor surveillance, consequently leading to an inhibition of the anti-tumor immune responses." (PMID 37954069, 2023). "Nevertheless, several studies have demonstrated that tumor cell-derived EVs could carry tumor antigens and then promote tumor immunity through CD8(+) and CD4(+) T cells, which could kill tumor cells and frustrate the progression of tumors." (PMID 36986843, 2023). "However, we detected an increase in tumor-specific CD39+CD8+ and CD39+CD4+ T cells in the spleens of cured animals." (PMID 36068918, 2023). "ACM derived from OGJ patients with early-stage tumours and late-stage tumours did not significantly affect the frequency of CD4+ Treg cells compared with untreated cells." (PMID 36790524, 2023). "Similarly, dominant peripheral T cell clonotypes, in line with their phenotypical counterparts in the tumour, were concentrated within peripheral effector T cells (CD8 TEM, CD8 TEMRA, CD4 TCYTO)." (PMID 38030622, 2023). "Transient antibody-mediated depletion of CCR2+ monocytes impaired the efficacy of CD4 ACT therapy to a greater extent than the depletion of Ly6G+ neutrophils, supporting a predominant role of iNOS-expressing monocytes and macrophages for tumour eradication." (PMID 37316667, 2023). "To determine whether this concomitant tumor immunity was affected by Tcm or CD103+ CD8 T cell formation, we repeated the experiment with either CD4 depletion at challenge to limit Tcm formation, or CD40L blockade to limit Tcm and CD103+ CD8 T cells." (PMID 37072485, 2023). "Further study of CD11b+ DCs from lymph nodes demonstrate that they have the potential to present tumor antigens to CD4 T-cells but without inducing their differentiation, due to the presence of Treg." (PMID 37190135, 2023). "While CD4+ T cells have multiple known roles in antitumor immunity, they have not yet been prioritized for targeting tumor neoantigens in most vaccination strategies." (PMID 38063199, 2023). "A study of the carcinogenesis in pancreatic islets showed that T-antigen-specific CD4+ Th cells induced growth arrest of proliferating tumor cells without any significant cytotoxic effects." (PMID 36769195, 2023). "The level of tumor CD4+ T cells was lower than that of stromal CD4+ T cells at baseline, while it was not different during combination." (PMID 37275884, 2023). "Hence, there are mixed reports on the need and contributions of CD4+ and CD8+ T cells in the described syngeneic tumor models." (PMID 37244905, 2023). "Interestingly, while CD4+ and CD8+ T cell frequencies were comparable within tumor-infiltrating M28z and MBBz CAR T cells, the CD4+ subset was predominant within M1xx CAR T cells (p<0.05)." (PMID 36746513, 2023). "Under conditions of active anti-tumor immunity, DDR scores have been found to positively correlate with immune-related biomarkers, such as the number of T cells (such as CD4+ activated memory cells, CD8+ cells), T-cell receptor repertoire, PDL1 expression, and broad immune infiltrate." (PMID 36900418, 2023).
tumor (continued). "CD4( +) T memory cells have already been reported to confer vital functions on malignancy immune regulation, including participating in the activation of CD8 + T and NK killing cells, involving in the tumour immunological reactions." (PMID 37438709, 2023). "The numbers of CD4+ T-cells and TIL-Bs in TLS were strongly correlated, and in TLS with GC, but not in TLS without GC, TIL-Bs interacted with each other and with CD4+ Tconv, suggesting that TLS with GCs play a key role in humoral anti-tumor immunity." (PMID 38188682, 2023). "An optimal response to a tumor-specific neoantigen requires both CD8+ and CD4+ T cells." (PMID 37215122, 2023). "In contrast, increased CD4+ OT-II T cells accumulation in response to NEC immunization was detected in the draining lymph nodes and tumor when OT-II T cells were adoptively transferred the day prior to tumor challenge." (PMID 38196632, 2023). "Large numbers of CD8+ T cells which supposedly should kill tumor was not sufficient to inhibit tumor due to the deficit in functional CD4 helper cells." (PMID 36960410, 2023). "However, natural and immunotherapy-induced anti-tumor responses depend on tumor antigen-specific CD8+ and CD4+ T cell activity." (PMID 38328405, 2023). "We observe that the same CD40L-dependent signals are necessary to mediate concomitant tumor immunity, and that CD4 T cells are not essential for concomitant tumor immunity." (PMID 37072485, 2023). "In addition, ERO1A mRNA level was negatively correlated with genes that define anti-tumor immunity and immune infiltrates, including CD8+ T, B, and NK cells, whereas it was positively correlated with CD4+ T cells." (PMID 37769655, 2023). "The T-cell flow cytometry analysis showed, in TIOs+NIR1 treated tumour beds, the population of CD3+, CD4+ and CD8+ T cells could be increased to the same level of TIOs+NIR3 treated mice, and the Treg cells also decreased." (PMID 37673934, 2023). "CD4+ T-cell activation (via tumor-specific MHC II) leads to increased interferon-gamma (IFN-γ) secretion, thus enhancing CXCL9 production and PD-L1 expression, culminating in an immunotherapy-sensitive tumor phenotype." (PMID 37761972, 2023). "CD4 and CD8 T lymphocytes maintain adaptive cellular immune responses against neoplasms." (PMID 36678242, 2023). "CR significantly slowed down the tumor growth of B16-OVA without affecting both CD4+ and CD8+ T cell infiltration into the tumor." (PMID 37630828, 2023). "In BLCA mice models, the combination of oxaliplatin and anti-PD-1 inhibitor could restrict tumor growth and enhance the infiltration of immune cell populations in TIME, including CD3+ T cells, CD4+ T cells, CD8+ T cells, DC cells, and NK cells." (PMID 36960067, 2023). "In vivo, antibody depletion of NK cells, neutrophils, and CD8+ T cells, but not CD4+ T cells, induces IL-28-mediated inhibition of tumor growth." (PMID 37809098, 2023). "IL-21 is secreted by CD4+ T cells, directing the differentiation of cytolytic CX3CR1+CD8+ T cells (a subset of CD8+ T cells) to protect against persistent viral infection and exert anti-tumor activity." (PMID 38328405, 2023). "Therefore, T cells can retard immune response on the tumor by inhibiting the action of both tumor-specific (CD8+ cytotoxic T lymphocytes and CD4+ T helper cells) and tumor-unspecific effector cells such as natural killer (NK) and NK T cells." (PMID 37111677, 2023). "This tumor control required CD4, but not CD8 T cells, thereby allowing us to assess the role of CD4 T cells in tumor control independent of their helper function." (PMID 37185301, 2023). "The combined treatment significantly delayed tumor growth and enhanced antitumoral immunity by lowering PD-1 expression levels in tumor-infiltrating CD4 T cells but not in CD4 T cells isolated from lymph nodes of tumor-bearing mice." (PMID 37147330, 2023).